SPHK2 (sphingosine kinase 2)
Diseases named in the same sentence as SPHK2 in open-access papers (continued):
Sharing a sentence is not in itself a finding about the gene and the disease.
multiple myeloma (15 papers, 2016 to 2025). "SPHK2 is also implicated in multiple myeloma and the SPHK2 inhibitor, (R)-FTY720 methyl ether (ROMe), induces the autophagic death of T-ALL cell lines." (PMID 32260399, 2020). "On the contrary, in large granular lymphocyte leukemia or multiple myeloma SPHK2 inhibition downregulates MCL-1 expression." (PMID 37020867, 2023). "The different mechanisms leading to ER stress induced by bortezomib and SphK2 inhibition provided the rationale for concomitantly targeting both pathways in myeloma demonstrating a synergistic anti-MM effect in vitro and in vivo." (PMID 35756630, 2022). "Similar to SPHK1, SPHK2 was also found to be overexpressed in primary CD1381 multiple myeloma cells, as well as in 7 different myeloma cell lines." (PMID 36361536, 2022). "Both pharmacological inhibition of SPHK2 using ABC294640 or K145, and genetic interference of SPHK2 have shown effects on myeloma cell proliferation and viability." (PMID 30062053, 2018). "SphK2 has also been reported to play a supportive role in MM cell survival since SphK2-specific inhibition induced apoptosis in MM cells in vitro and suppressed myeloma tumor growth in vivo in mouse myeloma xenograft models." (PMID 35159039, 2022). "Moreover, the combination of bortezomib, a proteasome inhibitor and FDA approved drug for multiple myeloma, with inhibition of SPHK2 synergistically increased ER stress and apoptosis." (PMID 36361536, 2022). "Venkata and collaborators recently showed that SphK2 represents a potential therapeutic target for the treatment of MM by using ABC294640, a SphK2-specific inhibitor that exhibited anti-myeloma activity in primary human CD138+ cells and in in vivo mouse xenograft models." (PMID 35756630, 2022). "We have recently demonstrated that inhibition of SphK2 induces unrecoverable ER stress leading to apoptosis of multiple myeloma cells and this ER stress-inducing mechanism is most likely also applicable to a range of cell types, including those of ALL, thus impacting on its development in our model." (PMID 29441205, 2018). "The mechanism of Sphk2 inhibitors in leukemia is mainly based on increasing autophagic death, as seen for example in T cell-acute lymphocytic leukemia, or a decrease in cell proliferation and induction of apoptosis in multiple myeloma cells." (PMID 29029455, 2017). "highlights SphK2 overexpression in MM cell lines and in primary human BM CD138+ myeloma cells and its contribution to the survival and proliferation of these cells." (PMID 35756630, 2022). "Today, SphK2 inhibitor ABC294640 has undergone clinical trials to treat pancreatic cancer and multiple myeloma (NCT01488513 and NCT02757326)." (PMID 35201458, 2021). "While the majority of drugs targeting these enzymes remain in pre-clinical development, others such as the SPHK2 inhibitor, ABC294640 are under investigation in clinical trials for relapsed/refractory multiple myeloma (NCT02757326)." (PMID 30062053, 2018). "The majority of these studies have focussed on solid tumors, however there are reports in haematological malignancies including multiple myeloma and T-ALL, and we have previously reported a role for SphK2 in B lineage ALL using a BCR/ABL1-dependent model." (PMID 29441205, 2018). "Recently, it was shown that inhibition of SphK2 by ABC294640 results in decreased c-Myc expression in acute lymphoblastic leukemia, multiple myeloma and prostate cancer cells." (PMID 27517489, 2016).
hepatocellular carcinoma (14 papers, 2014 to 2025). A malignant tumor that arises from hepatocytes. "Pharmacologic inhibition of SphK2 reduces tumor growth in pre-clinical models for breast, prostate, colon, and hepatocellular cancers, as well as KSHV-associated PEL." (PMID 25010828, 2014). "Another study found compared with that in healthy volunteers, the level of SphK2 was reduced in the liver of patients with alcoholic cirrhosis and hepatocellular carcinoma, and SphK2 deficiency could aggravate liver injury induced by alcohol." (PMID 34054552, 2021). "We also confirmed the interaction between AHR and SPHK2 using an additional cell line (Huh7, a human hepatoma cell line, and a different AHR agonist, indolo[3,2‐b] carbazole (ICZ)." (PMID 39207053, 2024). "In particular, activation of the NF-κB pathway by increased SphK2 expression was similar to that observed in regorafenib-resistant hepatocellular carcinoma-derived cells." (PMID 38280459, 2024). "The upregulation of HIF-2α and Epo synthesis by Sphk2 knockdown was confirmed in the human hepatoma cell line Hep3B, which is well-established to upregulate Epo production under hypoxia." (PMID 35682566, 2022). "For example, targeting SphK2 reversed the acquired resistance to regorafenib in hepatocellular carcinoma." (PMID 35178477, 2022). "SPHK2 targeting by ABC294640 significantly reduces resistance to regorafenib in an in vivo model of hepatocellular carcinoma (HCC)." (PMID 34737957, 2021). "Inhibition of SphK2 can disrupt lipid efflux in hepatocellular carcinoma cells and induce lipotoxic accumulation, suggesting that the SphK2-mTORC2 axis may serve as a novel target for metabolic reprogramming in liver cancer." (PMID 41234914, 2025). "In the treatment of hepatocellular carcinoma (HCC), SphK2 inhibitors show important potential." (PMID 41234914, 2025). "SphK2 is the main isoform of SphK in the liver, accounting for 90% of its total activity Studies have shown that SphK2 drives the progression of non-alcoholic fatty liver disease (NAFLD)-related hepatocellular carcinoma (HCC) through dual mechanisms." (PMID 41234914, 2025).
glioma (13 papers, 2019 to 2025). A benign or malignant brain and spinal cord tumor that arises from glial cells (astrocytes, oligodendrocytes, ependymal cells). "We simultaneously co-transfected glioma cells with a miR-708 mimic and a pcDNA3.1-SPHK2 vector that encoded full-length SPHK2 except for its 3′-UTR." (PMID 31171769, 2019). "However, we revealed that SPHK2 was significantly associated with overall survival rate in lower grade glioma patients, instead of that in higher grade glioma patients." (PMID 31171769, 2019). "Our analysis revealed that SPHK2 knockdown altered the expression of 12 exosomal miRNAs in glioma cells." (PMID 41476593, 2025). "We also verified that miR-137 is a diagnostic tumor-suppressive microRNA (miRNA) that targets SPHK2 to promote M1-type TAM polarization, which successfully established glioma cell lines with SPHK2 knockdown using the lentiviral infection method." (PMID 41476593, 2025). "In conclusion, our study establishes that SPHK2 knockdown in glioma cells significantly reshapes the exosomal miRNA cargo, underscoring its role as a pivotal regulator of miRNA sorting and secretion." (PMID 41476593, 2025). "The heatmap showed two upregulated and 10 downregulated miRNAs in glioma cells with SPHK2 knockdown." (PMID 41476593, 2025). "Recent studies have shown that sphingosine kinase 2 (SPHK2) is positively associated with TAM infiltration and glioma proliferation." (PMID 41476593, 2025). "SPHK2 knockdown of the human glioma cell line U373 was performed using short hairpin RNA (shRNA) lentiviruses." (PMID 41476593, 2025). "This induced growth arrest and apoptosis, specifically in IDH-mutant gliomas highlighting a metabolic vulnerability characterized by elevated ceramides and decreased SPHK2 expression in IDH-mutant compared to IDH-wildtype gliomas." (PMID 39723240, 2024). "In gliomas, ubiquitination of sphingosine kinase 2 (SphK2) by NEDD4L was shown to suppress invasion of cells via blocking the AKT/β-catenin pathway." (PMID 37580757, 2023). "While both SPHK1 and SPHK2 participate in the phosphorylation of sphingosine, the expression of SPHK1 is elevated in IDHwt glioma patients and is highly correlated with a worse prognosis compared to SPHK2." (PMID 36012521, 2022). "This study discovered a metabolic vulnerability involving the global elevation of ceramides, in conjunction with suppressed SPHK2 expression in the representative IDHmut gliomas compared to IDHwt." (PMID 36012521, 2022). "Compared with the vector, overexpression of NEDD4L suppressed glioma U251 cell viability and invasion, while SphK2 overexpression promoted glioma cell viability and invasion." (PMID 34305532, 2021). "The results of flow cytometry assay also showed that NEDD4L abolished the inhibition of glioma cell apoptosis and death mediated by SphK2." (PMID 34305532, 2021). "Our results also showed that ubiquitination of SphK2 negatively regulated glioma malignancy through suppressing the AKT/β-catenin pathway." (PMID 34305532, 2021). "Similar to SphK1, SphK2 also targeted the AKT pathway to regulate glioma cell proliferation and EMT." (PMID 34305532, 2021). "In gliomas, both SphK1 and SphK2 were abnormally upregulated in tumor tissues and cell lines, and a higher expression of SphKs means lower survival times of glioma patients." (PMID 34305532, 2021). "Compared with SphK2 overexpression alone, in combination with NEDD4L and SphK2, overexpression reversed SphK2-mediated promotion of glioma viability and invasion." (PMID 34305532, 2021). "To identify potential modulators of SphK2, we overexpressed SphK2 in glioma U251 cells and performed mass spectrometry analysis of binding complexes formed with SphK2." (PMID 34305532, 2021). "NEDD4L overexpression repressed glioma proliferation and invasion and promoted glioma apoptosis via the SphK2/AKT/β-catenin pathway in vitro and in vivo." (PMID 34305532, 2021).
glioma (continued). "In this study, we overexpressed SphK2 in glioma cells and performed mass spectrometry to analyze the binding complexes formed with SphK2." (PMID 34305532, 2021). "Cell viability assay, flow cytometry assay, and transwell invasion assay were performed to illustrate the roles of NEDD4L-mediated SphK2 ubiquitination in glioma viability, apoptosis, and invasion, respectively." (PMID 34305532, 2021). "First, we found that NEDD4L expression levels were decreased in glioma cells compared with normal brain cells, whereas SphK2 expression was the opposite." (PMID 34305532, 2021). "Ubiquitination of SphK2 mediated by NEDD4L overexpression suppressed glioma cell viability and invasion but promoted glioma apoptosis." (PMID 34305532, 2021). "The ubiquitination of SphK2 mediated by NEDD4L negatively regulated glioma malignancy via the AKT/β-catenin pathway." (PMID 34305532, 2021). "The tumor oncogene sphingosine kinase 2 (SphK2) was previously found to be upregulated in glioma tissues and enhance glioma cell epithelial-to-mesenchymal transition through the AKT/β-catenin pathway." (PMID 34305532, 2021). "Taken together, all these results supported our findings that NEDD4L-mediated SphK2 ubiquitination functioned as a tumor suppressor in gliomas." (PMID 34305532, 2021). "We explored the functional impact of SPHK2 in glioma cells by knocking down SPHK2 expression with small interfering RNA (siRNA) in LN382 and GBM-GY cells." (PMID 31171769, 2019). "To examine this possibility, we re-introduced SPHK2 into the LV-miR-708 cells and observed that SPHK2 overexpression reversed the tumor-suppressing effects of miR-708 on glioma cells." (PMID 31171769, 2019). "Building on previous findings, this study aimed to determine whether SPHK2 regulates the release of exosomal miRNAs from glioma cells and to identify specific miRNAs that could potentially participate in macrophage polarization." (PMID 41476593, 2025). "Our aim was to reveal whether SPHK2 affects exosome microRNA (miRNA) release from glioma cells and which miRNAs regulated by SPHK2 could mediate the polarization of macrophages around glioma cells." (PMID 41476593, 2025). "Therefore, the collective evidence positions SPHK2 as a key regulator of glioma growth through its influence on the polarization of TAMs." (PMID 41476593, 2025). "Based on the literature and our previous research, in this study, we demonstrate whether and which exosome miRNAs SPHK2 regulates in glioma cells." (PMID 41476593, 2025). "Hypoxia increases the production and release of S1P in glioma cells, upregulates SphK1 that promotes the migration of endothelial cells, stimulates SphK2 expression and S1P release in adenocarcinoma cells, and stimulates SphK1 and SphK2 expression in pulmonary smooth muscle cells." (PMID 39660488, 2024). "Ubiquitination of SphK2 decreased its protein levels, which might have an effect on the roles of SphK2 in glioma." (PMID 34305532, 2021). "This raises our interests to explore the ubiquitination of SphK2 in gliomas." (PMID 34305532, 2021). "Hence, our results indicated that ubiquitination of SphK2 regulated glioma malignancy via indirectly targeting the AKT/β-catenin pathway." (PMID 34305532, 2021). "SphK2 has previously been reported to be upregulated in glioma tissues and played as an oncogene." (PMID 34305532, 2021). "Moreover, NEDD4L overexpression induced the ubiquitination of SphK2 reversing the promotion of glioma cells mediated by SphK2." (PMID 34305532, 2021). "Moreover, further results suggested that ubiquitination of SphK2 regulated glioma malignancy via the AKT/β-catenin pathway." (PMID 34305532, 2021). "This study reveals that NEDD4L mediates SphK2 ubiquitination to regulate glioma malignancy and may provide some meaningful suggestions for glioma treatment." (PMID 34305532, 2021). "Moreover, SphK2 overexpression enhanced glioma cell epithelial-to-mesenchymal transition through the AKT/β-catenin pathway, a downstream target of S1P." (PMID 34305532, 2021).
glioma (continued). "In addition, SPHK2 overexpression counteracted the effect of miR-708 on glioma cell growth and invasion." (PMID 31171769, 2019). "We revealed that SPHK2 down-regulation inhibited glioma cell growth and invasion." (PMID 31171769, 2019). "Taken together, these data suggest that SPHK2 functions as an oncogene in glioma cells." (PMID 31171769, 2019). "Because SPHK2 down-regulation mimicked the effect of miR-708 on glioma cells, we hypothesized that miR-708 directly targets SPHK2." (PMID 31171769, 2019). "We observed that SPHK2 down-regulation inhibited glioma cell growth and invasion." (PMID 31171769, 2019). "Restoration of miR-708 inhibited cell growth and the epithelial-to-mesenchymal transition (EMT) phenotype in glioma, and suppression of the sphingosine kinase 2 (SPHK2)/AKT/β-catenin pathway might be a critical function of miR-708 in glioma." (PMID 31171769, 2019). "Therefore, we propose that the SPHK2/AKT/β-catenin axis mediates the effect of miR-708 on glioma cell growth and invasion." (PMID 31171769, 2019). "Recent research has shown that SPHK2 mediating the S1P signaling pathway activates the maturation of secretion, molecular loading, and secretion, which is important in many biological functions of glioma, suggesting that SPHK2 may affect macrophage polarization through exosome release and function." (PMID 41476593, 2025). "Moreover, NEDD4L-mediated ubiquitination of SphK2 inhibits glioma cell survival and invasion." (PMID 38027016, 2023). "Moreover, NEDD4L-mediated ubiquitination of SphK2 promotes glioma cell apoptosis." (PMID 38027016, 2023). "Our observation that higher SPHK1 expression results in worse prognosis is in accordance with previous findings showing that increased SPHK1, but not SPHK2, correlates with lower progression-free survival in GB and has been associated with increased glioma grade." (PMID 36672428, 2023). "Thus, we speculated that NEDD4L-mediated ubiquitination of the SphK2 protein might reverse its role in gliomas." (PMID 34305532, 2021). "Interestingly, we also observed a negative association between miR-708 and SPHK2 expression in glioma tissues." (PMID 31171769, 2019). "Our previous study found that the expression level of SPHK2, the macrophage marker CD68, and the M2-type TAM (anti-inflammatory tumor-promoting) markers in glioma tissues were higher than those in the control brain tissue." (PMID 41476593, 2025). "The foundation for this inquiry includes reports that SPHK2 knockdown suppresses GB proliferation and our own observation linking SPHK2 to TAM infiltration and glioma progression." (PMID 41476593, 2025). "Ubiquitination of the tumor oncogene sphingosine kinase 2 (SphK2) mediated by NEDD4L overexpression inhibits glioma cell viability and invasion as well as promotes glioma cell apoptosis." (PMID 38027016, 2023). "SphK2 expression is upregulated in glioma tissues and promotes EMT in glioma cells via the AKT/β-catenin pathway." (PMID 38027016, 2023). "For example, METTL3 regulates SOX2 mRNA in glioma stem cell maintenance and colorectal tumor progression, LEF1 in osteosarcoma progression, AFF4/NF-kB/MYC in bladder cancer, and SPHK2 in gastric cancer." (PMID 36183833, 2022). "Another study on gliomas demonstrated that the silencing of miR-708 promoted cell growth and EMT transition by activating the SPHK2/AKT/β-catenin pathway." (PMID 36101746, 2022). "In summary, our data provide the first evidence that the EZH2/miR-708/SPHK2/AKT/β-catenin axis controls growth and invasion in glioma cells." (PMID 31171769, 2019). "For example, epithelial-mesenchymal transition (EMT) is an important factor that plays an important role in glioma progression, and inhibition of microRNA-708 in exosomes has been reported to increase cell proliferation and EMT in gliomas by promoting the SPHK2/AKT/catenin pathway." (PMID 37727789, 2023).
glioma (continued). "Overexpression of SphK2 significantly promoted glioma growth, and this could be partially reversed following NEDD4L in combination with SphK2 overexpression." (PMID 34305532, 2021). "First, we found that SPHK2 overexpression increased phosphorylated Akt, phosphorylated GSK3-β and β-catenin levels, whereas SPHK2 inhibition decreased phosphorylated Akt, phosphorylated GSK3-β, and β-catenin levels in glioma cells." (PMID 31171769, 2019). "Our study elucidated a link between miR-708 inactivation and the SPHK2/AKT/β-catenin pathway, thereby providing new insight into the potential use of miR-708 in the development of novel therapeutic strategies for treating glioma." (PMID 31171769, 2019). "RT-PCR revealed that SPHK2 expression was elevated in glioma tissues compared with normal brain tissues." (PMID 31171769, 2019). "Interestingly, we also found that there was a negative correlation between miR-708 and SPHK2 expression in glioma tissues." (PMID 31171769, 2019).